REN (renin)
Diseases named in the same sentence as REN in open-access papers (continued):
Sharing a sentence is not in itself a finding about the gene and the disease.
diabetes (continued). "Renin–angiotensin system blockers, beta drugs, statins, antivascular endothelial growth factor drugs, and antioxidants can inhibit the occurrence of microvascular complications in diabetes." (PMID 38645437, 2024). "Cd exposure can activate inflammatory response, disturb renin–angiotensin–aldosterone system, and produce mutagenic effect, which may be conducive to the development of diabetes and its complications." (PMID 38903987, 2024). "Univariate analysis revealed that IAP (OR = 1.787, p < 0.001), diabetes status (OR = 5.314, p < 0.05), use of renin-angiotensin system inhibitor (RASi) medications (OR = 0.282, p < 0.05), and proteinuria (OR = 4.167, p < 0.05) were influencing factors for RRF decline." (PMID 38321869, 2024). "The important role of the renin–angiotensin system in diabetes was demonstrated by the evidence provided by ACEIs and ARBs in the treatment of diabetic nephropathy, in which they determined the decrease in proteinuria, renoprotective effects, and the regression of this complication." (PMID 39062156, 2024). "Nevertheless, other homeostatic systems affecting intrarenal RAS activity, such as the copeptin-vasopressin axis, may contribute to the elevation of renin levels, thereby promoting the progression of renal damage, especially in diabetes." (PMID 38396894, 2024). "Renin–angiotensin system inhibitors and sodium-glucose cotransporter-2 inhibitors are recommended for patients with albuminuria, and statins are recommended for all patients with diabetes and CKD." (PMID 37409235, 2023). "On the other hand, the significant difference between urinary EGF/creatinine levels in the children with obesity or diabetes, seems to confirm the difference in physiological regulation of blood pressure in the 2 groups, salt-sensitivity-driven in the obese versus renin-induced in the T1DM patients." (PMID 36996194, 2023). "As for subtypes of IS, IVW preliminarily identified six categories significantly associated with SVS, which were beta blocking agents, drugs used in diabetes, agents acting on the renin-angiotensin system, diuretics, HMG CoA reductase inhibitors, and calcium channel blockers." (PMID 37020515, 2023). "Factors associated with hyperkalemia in patients with CKD, in addition to reduced kidney function, include concomitant medication use (e.g., renin–angiotensin–aldosterone system inhibitors and potassium-sparing diuretics), and comorbidities (e.g., diabetes and cardiovascular disease)." (PMID 37020294, 2023). "Higher levels of renin (log10renin: 3.27±0.59 vs 2.82±0.69 pg/mL, p<0.001) were found in diabetes." (PMID 37586847, 2023). "The recent findings showing that anomalies in microglia‐vascular interactions occur during early diabetes are consistent with the important role of renin‐angiotensin in diabetes and may suggest the importance of a more targeted cellular treatment." (PMID 36349522, 2023). "We hypothesize that SARS-CoV-2 exacerbates diabetes-induced cerebrovascular oxidative stress and inflammation via activation of the destructive arm of the renin-angiotensin-aldosterone system (RAAS) and Toll-like receptor (TLR) signaling." (PMID 38003584, 2023). "Furthermore, renin instability has been shown to decrease podocyte survival and accelerate diabetes-induced renal damage, while HDAC-4 signaling is involved in renin stability in the progression of diabetes-induced podocyte injury." (PMID 38074159, 2023). "Disturbance of glucose homeostasis, inflammation and activation of the renin-angiotensin-aldosterone system in diabetes mellitus could contribute to severe forms of COVID-19 infection." (PMID 37104352, 2023). "Renin-angiotensin system blockers (ACE inhibitors or ARBs) and SGLT2 inhibitors have been shown to slow the progression of CKD and reduce CV risk in individuals with diabetes and CKD, but the significant residual risk remains." (PMID 36719097, 2023).
diabetes (continued). "Medication classes used in diabetes and cardiovascular diseases (lipid modifying agents, agents acting on the renin-angiotensin system, beta blocking agents and calcium channel blockers) were frequently claimed across all groups, with lipid modifying agents being the most frequent category." (PMID 37408840, 2023). "In addition, this study demonstrated the causal relations between beta blocking agents, drugs used in diabetes, agents acting on the renin-angiotensin system, diuretics, calcium channel blockers, and increased SVS risk." (PMID 37020515, 2023). "The aims of the study are to assess the real-world effects of combination SGLT2i and GLP-1RA therapies for diabetes management on kidney end points, glycemic control, and weight in people with type 2 diabetes who are being treated with renin-angiotensin system blockade medication." (PMID 35852840, 2022). "Future strategies that increase soluble ACE2 may reduce accelerated atherosclerosis in diabetes and other states in which the renin angiotensin system is upregulated." (PMID 35624851, 2022). "In diabetes, there is a marked increase in prorenin/renin levels, which may contribute to the development of diabetic nephropathy via interaction with the renal PRR." (PMID 35455055, 2022). "Lipid modifying agents (13.0%, n = 399), agents acting on renin-angiotensin system (9.5%, n = 291), beta blockers (9.5%, n = 291), drugs used in diabetes (7.2%, n = 222), and diuretics (6.6%, n = 201) were the most prescribed therapeutic subgroups (WHO ATC level 2 classification)." (PMID 35348764, 2022). "The role of diabetes-induced hyperglycaemia in the pathogenesis of atherosclerosis can be due to local and systemic factors via inflammation, oxidative stress, and changes in the renin-angiotensin system." (PMID 36552060, 2022). "It is uncertain if the combination of sodium‐glucose co‐transporter 2 inhibitors (SGLT2‐Is) and renin‐angiotensin‐aldosterone system inhibitors (RAAS‐Is) provides better cardio‐renal clinical outcomes in people with type 2 diabetes mellitus (T2DM) compared with SGLT2‐Is alone." (PMID 34636161, 2022). "We hypothesized that diabetes activates the intestinal renin–angiotensin system (RAS), contributing to gut pathology." (PMID 35682739, 2022). "Diuretics, Antithrombotic agents, Drugs used in diabetes, and Agents acting on the renin-angiotensin system were the medication classes, which accounted for more than half of the medication classes associated with preventable DRAs related to treatment effectiveness." (PMID 35770091, 2022). "A recent study where empagliflozin was added to RAS inhibitors for 12 weeks in people with CKD with or without diabetes and albuminuria demonstrated a significant increase in angiotensin 1–7, angiotensin I levels and upregulation of plasma renin activity in people with the diabetes." (PMID 36247425, 2022). "Hyperglycemia has been reported to increase renin release in the kidney, and serum angiotensin converting enzyme activity is increased in patients with diabetes mellitus compared to healthy subjects, suggesting activation of the renin angiotensin aldosterone system in these subjects." (PMID 34255808, 2021). "Renin activity in plasma increased by anti-hypertensive medications in subjects with diabetes." (PMID 33933156, 2021). "In addition to stimulating the renin–angiotensin–aldosterone system, diabetes mellitus, anterior infarction and its extensive early spread, and persistent occlusion of the intra-infarct artery exacerbate adverse myocardial remodeling." (PMID 34844646, 2021). "The renin-angiotensin system (RAS) is related to diabetes, metabolic disorders and periodontitis." (PMID 34572060, 2021). "In addition to its endorsement by the PQA PDC metrics are required by the Centers for Medicare & Medicaid Services (CMS) for renin–angiotensin system antagonists, statins, and all diabetes drugs." (PMID 34965882, 2021).
diabetes (continued). "However, inactivation of the tubuloglomerular feedback and activation of the renin–angiotensin–aldosterone system (RAAS) appear to be major mechanisms for glomerular hyperfiltration in early diabetes." (PMID 34884571, 2021). "Because both PRR and renin are both increased in CD cells in diabetes, it is reasonable that both may contribute to distal AngII formation." (PMID 34179130, 2021). "One study has shown that the use of antagonists of the renin–angiotensin–aldosterone system in diabetes contributes to a poor prognosis for COVID-19, and treatment of COVID-19 such as antivirals and corticosteroids may worsen glucose control in diabetics." (PMID 33282889, 2020). "Diabetes has also been shown to be associated with the activation of sympathetic nervous system (SNS) and increased outflow of catecholamines, and the activation of the renin–angiotensin system (RAS) and increased formation of angiotensin II." (PMID 32244448, 2020). "We evaluated adherence for noninsulin diabetes medications, renin-angiotensin system antagonists, and statins, as well as inappropriate use of high-risk medications in older adults and statin use in persons with diabetes." (PMID 32886060, 2020). "Evidence has suggested that AGT levels are increased in the intrarenal renin-angiotensin system in diabetes, and the enhanced intrarenal AGT levels may contribute to the progression of diabetic nephropathy." (PMID 32566679, 2020). "Long-term clinical outcomes in patients with acute myocardial infarction (AMI) and prediabetes or diabetes who received ß-blockers (BB) and renin–angiotensin system inhibitor (RASI) therapy after successful newer-generation drug-eluting stent (DES) implantation are limited." (PMID 33120966, 2020). "Individuals with a baPWV of ≥ 1800 cm/s (when comparisons were adjusted for age, sex, blood pressure, diabetes duration, eGFR, and use of renin-angiotensin system inhibitors) had a significantly higher risk of the progression of renal disease (HR = 8.480, p = 0.014)." (PMID 33102509, 2020). "Previous literature has predominantly focused on the vasoconstrictor arm of the RAS and shown that, in contrast to male rodent models of obesity and diabetes, females are protected from metabolic and cardiovascular derangements produced by angiotensinogen, renin, and angiotensin II." (PMID 31262355, 2019). "In our previous studies, we demonstrated that PRR could be contributing to the reported increase in the renin-angiotensin-system (RAS) activity in diabetes, with subsequent increase in TGFβ-connective tissue growth factor (CTGF) axis." (PMID 31800607, 2019). "Multiple interconnected pathways (e.g., polyol, AGEs, protein kinase C, renin-angiotensin system, and hexosamine pathway) that are activated by diabetes increase the expression of inflammatory and angiogenic mediators thereby inducing aberrant growth factor signaling." (PMID 31920963, 2019). "While there have not been direct studies linking the renin-angiotensin system and diabetes-induced arrhythmias, it is likely that they are intertwined since the renin-angiotensin system impacts nearly all contributing factors including cardiac remodeling, electrical remodeling and inflammation." (PMID 30534081, 2018). "In unadjusted analyses, PPI users were significantly older, had a higher rate of previous myocardial infarction and prevalence of diabetes, used more statins and renin-angiotensin system inhibitors, and had higher triglyceride and ADMA concentrations compared to non-users." (PMID 28588208, 2017). "Consistent with this view, direct renin inhibition with Aliskiren led to significant improvement of left ventricular hypertrophy and end-systolic volume only in groups of patients with diabetes." (PMID 27652272, 2016). "Another study suggests that diabetes might be associated with gender-specific decreases in KV1.5 levels in myocytes from male mice, and that this effect might be triggered by the renin-angiotensin system." (PMID 27724862, 2016).
diabetes (continued). "The renin-angiotensin system (RAS) plays a potential role in the development of end-organ damage, and tissue RAS activation has been suggested as a risk factor of several diseases including diabetes." (PMID 29259695, 2016). "In diabetes, the renin-angiotensin system (RAS) of the kidneys is activated." (PMID 26880862, 2016). "The tissue RA system is activated in diabetes, although plasma renin levels are paradoxically low." (PMID 25799069, 2015). "One possible reason for the high level of renin granulation of the afferent arterioles with the high level of angiotensin II in diabetes might be the enhanced downregulation of the AT1-B receptors of the SMC." (PMID 24587998, 2014). "We found that AGT mRNA was increased in the heart in diabetes almost twofold and this effect was reversed by miR-133a overexpression, suggesting that miR-133a inhibits activation of the local renin–angiotensin system." (PMID 24428157, 2014). "In this study we have employed transgenic mice with the human renin cDNA under the control of the transthyretin promoter (TTRhRen) and induced diabetes either through streptozotocin (STZ)-injections or by crossing with the OVE26 transgenic type 1 diabetes mouse on the susceptible FVB/n background." (PMID 25514595, 2014). "We reported that a renin inhibitor was more effective than an ACE inhibitor or ARB in preventing diabetes-induced cardiac superoxide production, apoptosis and fibrosis, suggesting the intracellular RAS as a possible residual risk factor in diabetes." (PMID 24215514, 2013). "The development of diabetes results in the formation of AGEs, oxidative stress, and the activation of the renin-angiotensin-aldosterone system (RAAS) within the kidney, which promotes progressive inflammation and fibrosis, leading to DN and declining renal function." (PMID 23737732, 2013). "Glomerular hyperfiltration and JGG renin activation are observed in diabetes." (PMID 24400038, 2013). "Only a renin inhibitor prevented diabetes-induced ANG II formation." (PMID 24215514, 2013). "Major clinical studies such as the UK Prospective Diabetes Study Group and others have shown beneficial effects of tight blood pressure control and antihypertensive renin-angiotensin system blockers on prevention and progression of retinopathy in diabetic patients." (PMID 22736937, 2012). "Blockade of the renin-angiotensin system (RAS) reduces the incidence of type 2 diabetes mellitus." (PMID 22768174, 2012). "In mRen-2 rats with streptozotocin-induced diabetes, the direct renin inhibitor aliskiren reduced renal gene expression of TGF-β1 and collagen I, but not collagens III and IV, and also reduced expression of the (pro-)renin receptor in glomeruli, tubules and cortical vessels." (PMID 20441574, 2010). "Thus, not only the renin-angiotensin system but also COX-2 contributes to the hyperfiltration state in diabetes." (PMID 27713354, 2010). "On the other hand, the renin-angiotensin system is activated in diabetes, and local angiotensin II production may lead to oxidative damage via the angiotensin II type 1 receptor." (PMID 20066132, 2008). "Diabetes mellitus is characterized by a combination of various somatic factors and factors that affect renal function such as advanced glycosylated end-product, pro-renin, cytokine, and nephrin expression, changes in the renin–angiotensin–aldosterone system, and FGF-23 degradation." (PMID 40685514, 2025). "Also, apoptosis was noted greater extent in people with diabetes with additional renin gene rats." (PMID 39337409, 2024). "Finally, studies suggest that inhibition of the renin–angiotensin system, including ACE inhibitors and ARBs like valsartan, may reduce diabetes incidence and cardiovascular risk." (PMID 39543645, 2024).
diabetes (continued). "Patients with diabetes have impaired innate immunity, chronic inflammatory responses, increased coagulation activity, and decreased angiotensin-converting enzyme II expression, wherein using renin-angiotensin-aldosterone system antagonists results in a poor COVID-19 prognosis." (PMID 38975064, 2024). "According to this indicator, Lipid Modifying Agents (C10) with 56.3%, Agents Acting on The Renin-Angiotensin System (C09) with 48.9%, Antithrombotic Agents (B01) with 35.7%, and Beta Blocking Agents (C07) with 30.1% were the most prevalent drug classes prescribed with Drugs Used in Diabetes (A10)." (PMID 37864248, 2023). "Thus, the renin–angiotensin–aldosterone system may be upregulated in diabetes, resulting in increased blood pressure through a direct effect mediated by angiotensin II, as well as indirectly through upregulation of sympathetic activity." (PMID 36376985, 2022). "The expression of renin is regulated by the levels of angiotensin II and renal perfusion pressure 23 and may be affected by physiological and pathological conditions including gender and diabetes mellitus." (PMID 34277961, 2021). "Demographic and clinical characteristics such as age, body mass index (BMI), blood aldosterone–renin ratio, blood potassium, blood glucose, blood lipid parameters, and history of diabetes mellitus (DM) were compared between the three groups." (PMID 34484110, 2021). "It should be noted that changes in the PRR and prorenin/renin observed during the very early phase of STZ- induced diabetes may let us evaluate in future studies whether these changes continue in later stages of the diabetic disease or in the presence of hyperglycemia." (PMID 34226610, 2021). "Furthermore, a strong relationship between diabetes mellitus, sympathetic over-activity, and AF is clear because metabolic changes lead to inflammatory reaction, endothelial dysfunction, and abnormal activation of the renin–angiotensin–aldosterone system." (PMID 32932837, 2020). "Indeed, diabetes and its associated hyperglycemia, insulin resistance, dyslipidemia, etc. all lead to altered biochemical pathways (polyol, AGEs, PKC, hexosamine, and renin-angiotensin system) that stimulate glial cell dysfunction." (PMID 31920963, 2019). "Renin–angiotensin–aldosterone system (RAAS) blockade with an angiotensin converting enzyme (ACE) inhibitor (ACEI) or angiotensin II type I receptor blocker (ARB) is the most widely used strategy to slow the progression of DKD in both type 1 diabetes mellitus or T2DM." (PMID 29665833, 2018). "In addition to blocking the renin-angiotensin system, telmisartan acts as a selective modulator of PPARγ, a central regulator of insulin and glucose metabolism and a well-known target of insulin-sensitizing drugs used to treat type 2 diabetes mellitus." (PMID 26846539, 2016). "However, we could not detect such a relationship between plasma renin activity and 24-h urinary sodium excretion, which could be partly attributed to the overall reduced plasma renin activity in individuals with diabetes." (PMID 28066329, 2016). "The objective of the present study was to investigate the role of the renin-angiotensin-aldosterone system, especially angiotensin II type 1a receptor (AT1aR) and mineralocorticoid receptor (MR) signaling, in left ventricular (LV) dysfunction induced by diabetes mellitus (DM)." (PMID 24664319, 2014). "Moreover, Müller cells express several RAS components, including (pro)renin and its receptor (P)RR, so that Müller cell dysfunction might contribute to ocular dysregulation in diabetes." (PMID 24968134, 2014). "However, to confirm the involvement of ANG II, we studied whether blocking ANG II synthesis with a renin inhibitor would prevent diabetes-induced cardiac dysfunction in AT1a-KO mice." (PMID 24215514, 2013).